TFAM (transcription factor A, mitochondrial)
Diseases named in the same sentence as TFAM in open-access papers (continued):
Sharing a sentence is not in itself a finding about the gene and the disease.
diabetes (25 papers, 2011 to 2025). "A pivotal role of mitochondria in the pathogenesis of DM is supported by the findings that mtDNA mutations in humans, as well as pancreatic β-cell–specific knockout of TFAM in mouse, cause diabetes." (PMID 35397560, 2022). "This MFN1/2 regulation occurs through the control of TFAM expression, which is vital for mtDNA maintenance and glucose regulation in diabetes." (PMID 41465559, 2025). "This is consistent with previously obtained data from obese patients: TFAM gene expression decreased in liver biopsies; mtDNA copy number also decreased in patients with type 2 diabetes mellitus." (PMID 36830933, 2023). "In diabetes, researchers have found that TFAM is ubiquitinated to reduce its transport to mitochondria." (PMID 36077101, 2022). "As demonstrated by our present study, diabetes causes a dysregulation in the expression of mitochondria-associated proteins in the ventricular myocardium, including PGC-1 α, Mn-SOD, TFAM, and MFN2." (PMID 36139819, 2022). "We previously demonstrated a decrease in PGC-1α/TFAM/mitochondrial biogenesis signaling in placenta of women with diabetes during pregnancy." (PMID 32762639, 2020). "We previously reported a decrease in the PGC-1α/TFAM mitochondrial biogenesis pathway in placenta of mothers with diabetes." (PMID 32762639, 2020). "This study aimed to investigate whether electroacupuncture (EA) can regulate skeletal muscle glucose metabolism through the AMPK/PGC-1α/TFAM signaling pathway in a rat model of type 2 diabetes mellitus (T2DM)." (PMID 41469741, 2025). "Indeed, niclosamide profoundly depressed TFAM expression, suggesting further damage to the mitochondrial biogenesis machinery in the presence of diabetes-induced hyperfusion." (PMID 38321058, 2024). "Diabetes is a major risk factor for triggering AD, and while its mechanism is unclear and direct evidence is lacking, we have reason to believe that TFAM is present in AD." (PMID 36077101, 2022). "In the diabetes-induced atrial, the agonist of PPAR-γ significantly increases mitochondrial biogenesis-related transcription factors (PGC1α, NRF1–2, TFAM) and mtDNA copy number and reduces mitochondrial ROS production." (PMID 35222272, 2022). "As expected, diabetes-induced down-regulation of NRF1 and TFAM mRNA expression was significantly altered by APX-115 or losartan." (PMID 29088780, 2017). "The bioactivity of KR was confirmed in Ins2Akita mice when administered long-term (from 4- to 8-months of diabetes), since KR but not vehicle control increased TFAM+ mitochondrial nucleoids in the diabetic retina (arrowheads)." (PMID 38321058, 2024). "To determine the mitochondrial function in the three groups, we evaluated the expression of mitochondria-associated proteins of ventricular tissue and found that the expression levels of PGC1-α, Mn-SOD, TFAM, and MFN2 showed a decreasing trend in the diabetes group compared to the control group." (PMID 36139819, 2022). "Exposure of male placental explants from mothers with diabetes to metformin increased H3K27 acetylation and PGC-1α/TFAM signaling, thus correcting the aberrant H3K27 acetylation in maternal diabetes and, consequently, expression of genes involved in placental mitochondrial biogenesis." (PMID 32433500, 2020). "Since mtDNA and TFAM deficiency is associated with neurodegenerative diseases, heart failure and diabetes, the finding that TMP can increase TFAM and mtDNA level in cells with defects in TFAM and mtDNA contents may have important therapeutic implications for human disease." (PMID 28465355, 2017).
Parkinson disease (25 papers, 2009 to 2025). A progressive degenerative disorder of the central nervous system characterized by loss of dopamine producing neurons in the substantia nigra and the presence of Lewy bodies in the substantia nigra and locus coeruleus. "Additionally, the knock-out of the mitochondrial transcription factor A (TFAM) within dopaminergic neurons causes progressive parkinsonism, the accumulation of protein inclusions, and dopaminergic neuron loss together with decreased mtDNA expression." (PMID 29751692, 2018). "The importance of mitochondrial biogenesis in neurons is also reflected by the observation that PGC-1α, NRF-1 and TFAM are downregulated in several neurodegenerative diseases, such as Huntington’s (HD), Parkinson’s (PD) and Alzheimer’s diseases (AD)." (PMID 34884861, 2021). "A TFAM-mediated “ProtoFection” was employed to deliver mtDNA into the mitochondria of cells representing a model of Parkinson’s disease and resulted in the restoration of mtDNA levels accompanied by the activation of mitochondrial biogenesis." (PMID 32824374, 2020). "Other studies reported TFAM activation with exercise in different pathological conditions other than parkinsonism." (PMID 33158454, 2020). "Mutations in this gene are associated with mtDNA depletion syndrome, and treatment with TFAM as an experimental therapy for Parkinson's disease has been suggested by data from a cellular model." (PMID 30310528, 2018). "TFAM plays a central role in the mtDNA stress-mediated inflammatory response and is involved in a variety of neurodegenerative conditions, including Alzheimer’s disease, Huntington’s disease, and Parkinson’s disease." (PMID 36430657, 2022). "However, in both cell and animal neurodegenerative models (Alzheimer’s, Parkinson’s, and Huntington’s diseases), increasing TFAM levels by mild overexpression or enzyme replacement considerably improved neural function and content." (PMID 32824374, 2020). "Extracellular signal regulated protein kinases (ERK1/2) reduce mitochondrial transcription by increasing phosphorylation of TFAM, which may have implications for Parkinson’s disease." (PMID 28465355, 2017). "In fact, a study from our group showed that dysfunctional mitochondria in a mouse model for Parkinson’s disease generated by knocking out the mitochondrial transcription factor A (TFAM) in dopaminergic neurons, did not recruit PARKIN." (PMID 26287188, 2015). "The MitoPark mice, with disruption of the gene for mitochondrial transcription factor A (TFAM) in dopaminergic neurons, are characterized by a marked depletion of mtDNA, impairment of oxidative phosphorylation, dopaminergic neuron degeneration and motor deficits that mimic human parkinsonism." (PMID 35513611, 2022).
ovarian carcinoma (20 papers, 2015 to 2025). A malignant neoplasm originating from the surface ovarian epithelium. "According to another study, increased TFAM expression in colorectal, endometrioid, pancreatic, and ovarian cancers is associated with an unfavorable prognosis with tumor metastasis." (PMID 37627097, 2023). "In clinical studies, lower mtDNA and TFAM is associated with poorer survival in ovarian cancer, oesophageal squamous cell carcinoma, colorectal cancer as well as oral squamous cell carcinoma." (PMID 34663785, 2021). "Last, the analysis of the association between the protein level of TFAM and the clinical stage of ovarian cancer based on CPTAC platform had a small sample size, particularly for the analysis involving stage I samples (n = 2), which might cause bias to the outcome obtained in this study." (PMID 39927160, 2025). "We showed that silencing TFAM can inhibit cell proliferation and promote apoptosis in ovarian cancer cells." (PMID 39927160, 2025). "The Kaplan‒Meier plotter database results showed that high expression of TFAM, HSPE1, and CYC1 was associated with an overall poor prognosis in ovarian cancer." (PMID 39927160, 2025). "This indicates that TFAM is involved in the lymphatic metastasis of ovarian cancer cells and can be used as a therapeutic target for lymphatic metastasis of ovarian cancer." (PMID 39927160, 2025). "The low expression of PGC1a and TFAM has been proposed as predictive markers for chemoresistance in the epithelial ovarian cancer subtype." (PMID 38589371, 2024). "Inhibiting TFAM expression in ovarian cancer promotes tolerance of chemotherapy drugs, attenuating mtROS and cisplatin-induced apoptosis." (PMID 38589371, 2024). "In that study, the authors documented increased mitochondrial biogenesis in ovarian cancer from an increase in the number of mitochondria along with increased PGC1α level, mitochondrial transcription factor (TFAM) level, and mitochondrial DNA (mtDNA) content." (PMID 38168673, 2024). "Based on TCGA, higher FABP4 and LPL and lower TFAM expression indicated poorer overall survival in patients with ovarian cancer." (PMID 36012230, 2022). "Conversely, in cases of epidermoid cancer, normal-small cell lung carcinoma, ovarian cancer, endometrial cancer, and breast cancer patients with TFAM-positive tumors had poorer overall survival." (PMID 32824374, 2020). "Studies on TFAM and ovarian cancer show that TFAM is also highly expressed in ovarian cancer." (PMID 39927160, 2025). "Therefore, after comprehensive consideration, we ultimately chose the TFAM gene as the target gene for subsequent research and explored its role in the occurrence and development of ovarian cancer." (PMID 39927160, 2025). "However, the role of TFAM in the lymphatic metastasis of ovarian carcinomas remains to be further explored." (PMID 39927160, 2025). "However, another study showed that knockdown of TFAM attenuated cisplatin-induced cell death in ovarian cancer cells." (PMID 38429817, 2024). "Proliferator-activated receptor gamma co-activator (PGC)-1α and mitochondrial transcription factor A (TFAM) are overexpressed in cisplatin-resistant ovarian cancer; similarly, PGC-1β confers the chemoresistance of lung cancer cells to cisplatin associated with mtDNA mutations." (PMID 35814444, 2022). "Moreover, curcumin treatment improved mitochondria biogenesis markers such as PGC-1α and TFAM and prevented the elevated of ET-1-mediated renal fibrosis and apoptosis in kidney isolated from cisplatin-treated ovarian cancer rat." (PMID 35517894, 2022). "In a human prostate cancer cell line and in tissue samples of ovarian cancer, TFAM was detected not only in the mitochondria, but also in nuclear chromatin, where it could regulate the expression of nuclear genes in addition to those in the mitochondria." (PMID 32824374, 2020).
ovarian carcinoma (continued). "Undoubtedly, the relevance of mitochondrial content for therapy response is evidenced by RNA expression analyses available in TCGA-OV data that show superior overall survival of ovarian cancer patients with high expression of the mitochondrial proteins TFAM and TIMM23." (PMID 31699970, 2019). "Therefore, we speculate that TFAM has the potential to become a drug target for the treatment of ovarian cancer." (PMID 39927160, 2025). "Therefore, we speculate that TFAM is involved in ovarian cancer metastasis by regulating tumor cell EMT." (PMID 39927160, 2025). "The protein levels of TFAM, HSPE1, and CYC1 were significantly increased in ovarian cancer tissues compared with normal tissues." (PMID 39927160, 2025). "To clarify the relationship between TFAM and EOC metastasis and EMT, in the second part of the experiment, we mainly explored the influence of TFAM on cell metastasis and EMT in ovarian cancer." (PMID 39927160, 2025). "The transcript content of mitochondrial genes such as PGC-1α, TFAM and COX4/1 was similar between groups, while the β-HAD level declined in ovarian cancer." (PMID 36012230, 2022). "Furthermore, the protein levels of TFAM, HSPE1, and CYC1 varied according to clinical stages of ovarian cancer." (PMID 39927160, 2025). "The results from the TCGA database showed that HSPE1 and CYC1 were significantly upregulated in ovarian cancer tissues, but TFAM was not statistically significant." (PMID 39927160, 2025). "The absence of expression of PGC-1α and TFAM has been reported in certain types of ovarian cancer." (PMID 37627097, 2023). "At cellular basis, decreased TFAM and mtDNA content led to lower mitochondrial activity resulting in greater lactate production, increased cell proliferation and enhanced metastatic capacity in breast cancer, intestinal cancer, oesophageal cancer, and cisplatin (CDDP) resistant ovarian cancer." (PMID 34663785, 2021). "However, the mechanism of TFAM in ovarian cancer has not been thoroughly studied." (PMID 39927160, 2025). "Although the TFAM and HSPE1 total protein expression levels of ovarian cancer tissues of each clinical stage were higher than those of normal tissues, the difference was only significant between normal and stage 3 tissues." (PMID 39927160, 2025). "This correlation was not clear with the ovarian cancer cell lines with low-OXPHOS subunit expression; specifically, the OVCAR-8 cells had normal levels and, in some cases, higher levels of PGC1α, TFAM, TUFM, and DARS2 protein expression." (PMID 36937395, 2023). "The chemoresistant clear-cell subtype of ovarian carcinoma was identified by the lack of expression of both PGC-1α and mitochondrial transcription factor A (TFAM)." (PMID 30400212, 2018).
heart failure (18 papers, 2016 to 2025). Inability of the heart to pump blood at an adequate rate to meet tissue metabolic requirements. "Genetic testing can identify mutations in mitochondrial genes, such as PGC-1α and TFAM, which are linked to cardiomyopathies and heart failure." (PMID 40076543, 2025). "Mice with T cell TFAM deficiency exhibited premature senescence phenotype in various tissues, with heart failure and increased levels of senescence markers." (PMID 38766643, 2024). "Interestingly, in human heart failure, another disease associated with high oxidative stress, high levels of 8-OHdG have been associated with low levels of TFAM protein and impaired mtDNA replication, with the resultant mitochondrial depletion shown to be independent of PGC-1α levels." (PMID 26893822, 2016). "Targeted disruption of TFAM, especially in the cardiac muscle, leads to a significant decrease in electron transport capacity, spontaneous cardiomyopathy, and heart failure." (PMID 37483656, 2023). "Conversely, the increased expression of TFAM in the heart tissue protects against heart failure induced by myocardial infarction." (PMID 37483656, 2023). "Despite the unsolved questions regarding the beneficial role of PGC-1α, the modulation of TFAM has shown interesting results in heart failure models." (PMID 36187489, 2022). "In this study, both in vivo and in vitro experiments proved that the key factors of PGC-1α/NRF1/TFAM signaling pathway were reduced in rats with heart failure, and QSG can upregulate the expression levels of these key factors." (PMID 35003305, 2021). "A decrease of TFAM expression has also been observed in several cardiac failure models with mitochondrial dysfunction." (PMID 34392401, 2021). "On the contrary, overexpression of TFAM exhibited therapeutic potential in heart failure, leading to the reduction of protease expression, ROS production, cytoplasmic calcium, and attenuated pathological hypertrophy in cardiomyocytes." (PMID 34392401, 2021). "Mitochondrial dysfunction has been reported in various forms of heart failure and TFAM overexpression showed an increased mtDNA copy number and cardioprotective effects against ROS-mediated mitochondrial oxidative stress in transgenic mice." (PMID 32824374, 2020). "TFAM also exhibited therapeutic potential in the reduction of protease expression involved in heart failure." (PMID 32824374, 2020). "In the heart failure model, inducing overexpression of cardiomyocyte TFAM has been reported to inhibit mitochondrial oxidative stress, and to improve cardiac function by suppressing pathologic cardiac hypertrophy 13,14." (PMID 32547324, 2020). "Our study showed that the relative amounts of TFAM and mtDNA decreased significantly in the mouse heart failure model after MI, and clearly proved that NEU1 inhibition can limit the decline of mtDNA levels and keep it at a normal level in the heart tissue of MI mice." (PMID 35548408, 2022). "Furthermore, sufficient evidence supports that the expression of PGC-1α and mitochondrial transcription factor A (TFAM) were reduced in many heart failure animal models and are accompanied by oxidative stress and mitochondrial dysfunction." (PMID 36091690, 2022). "Other models also correlated the TFAM gene regulation to mitochondrial diseases by showing that the overexpression of TFAM generates a protective effect on cell function in several disease models, such as type II diabetes, heart attack, and heart failure." (PMID 32649732, 2020). "Regarding the cardiac issue, recent studies have demonstrated that TFAM inhibits the NFAT4-MMP9 proteolytic pathway in TFAM transgenic mice subjected to aorticbanding-induced heart failure, reducing pathological cardiac remodeling like hypertrophy and other HF associated factors." (PMID 30845180, 2019). "Moreover, TFAM overexpression and TFAM acetylation mitigate mtDNA depletion and mitochondrial dysfunction in models of MI, volume overload, and transverse aortic constriction-induced heart failure." (PMID 41009042, 2025).
heart failure (continued). "In addition, TFAM overexpression in overload-induced heart failure models ameliorates mitochondrial ROS, decreases the expression and activity of the metalloproteinases MMP-2 and MMP9, and upregulates the expression of sarcoplasmic/endoplasmic reticulum Ca2+ ATPase 2a (SERCA2a)." (PMID 36187489, 2022). "When mitochondria become dysfunctional such as in failing hearts, TFAM level initially rises as a compensatory mechanism, but it progressively decreases as calcium mishandling and ROS production increase, as observed in later stages of heart failure, TFAM being lost in dysfunctional mitochondria." (PMID 30201689, 2018). "Carvedilol—a third-generation, nonselective β-blocker used in heart failure-stimulates mitochondrial biogenesis via the PGC-1α/TFAM axis in human umbilical vein endothelial cells." (PMID 41009042, 2025).